TBC1D3G (TBC1 domain family member 3G)
Description:
Acts as a GTPase activating protein for RAB5. Does not act on RAB4 or RAB11 (By similarity).
Tractability: Antibody: UniProt places it where antibodies can reach, with medium confidence; its Gene Ontology location is reachable by antibodies, with medium confidence. PROTAC: UniProt records ubiquitination sites on it.
Gene: Protein-coding gene on chromosome 17 (36,323,884 to 36,334,759, forward strand). Ensembl gene ENSG00000260287.
Subcellular location: Cell membrane
Subcellular location (Human Protein Atlas): Vesicles
Gene Ontology:
Molecular function: protein binding; GTPase activator activity
Cellular component: endosome; membrane; plasma membrane
Homologues: Orthologues: chimpanzee TBC1D3B (96% identical). Paralogues in human: TBC1D3H (99% identical), TBC1D3B (99% identical), TBC1D3D (99% identical), TBC1D3 (99% identical), TBC1D3C (99% identical), TBC1D3F (99% identical), TBC1D3I (99% identical), TBC1D3K (99% identical), TBC1D3L (99% identical), TBC1D3E (99% identical), TBC1D26 (30% identical), USP6NL (29% identical), and 33 more.